LEP (leptin)
Diseases named in the same sentence as LEP in open-access papers (continued):
Sharing a sentence is not in itself a finding about the gene and the disease.
Anxiety (105 papers, 2010 to 2026). Intense feelings of nervousness, tension, or panic often arise in response to interpersonal stresses. "Anxiety, which is caused by excessive worrying and physical symptoms due to increased sympathetic nervous system activation, is also influenced by plasma leptin levels, which affect stress, anxiety, and sadness." (PMID 40384809, 2025). "Moderate-severe anxiety symptoms are associated with high serum leptin levels in patients with type 2 diabetes." (PMID 35911226, 2022). "Based on the neuroendocrine functions of emotion regulation of leptin, mediation analysis showed that leptin was an indirect mediator in the association between clinical status and “somatic anxiety” symptoms." (PMID 35911226, 2022). "Instead, VTA LepR neurons primarily project to the central amygdala, and these neurons mediate effects of leptin on central amygdala associated behaviors, such as anxiety." (PMID 34276560, 2021). "Overall, this study found that variations in the leptin and leptin receptor genes are associated with measures of alcohol use, nicotine use, and anxiety." (PMID 34421692, 2021). "Symptoms of anxiety have been reported to be negatively associated with levels of leptin, while ghrelin was found to have an anxiolytic effect in animal studies following induced stress." (PMID 32110904, 2020). "Our results indicate that amygdalar and hippocampal synaptic plasticity are regulated in different ways by leptin deficiency in accordance with the different functions of these limbic structures in stress and anxiety." (PMID 32789683, 2020). "Our results also demonstrate that synaptic plasticity in the amygdala and in the hippocampus is regulated in different ways by leptin deficiency in accordance with the different functions of these limbic structures in stress and anxiety." (PMID 32789683, 2020). "For example, Wen-Dan-Tang can effectively alleviate the anxiety associated with insomnia by regulating the performance of the ghrelin receptor in the hypothalamus and the concentration of leptin in the brain." (PMID 30744039, 2019). "Higher cortisol, a physiological marker of anxiety/stress, has been associated with higher leptin concentrations in girls." (PMID 31547319, 2019). "These volumetric abnormalities were associated with behavioral indices of anxiety, increased leptin and FK506-binding protein 51 (FKBP51) levels, and reduced hippocampal blood vessel density." (PMID 27844058, 2016). "There is evidence that hormones associated with energy status of the mother such as insulin and leptin as well as expression of neurotransmitters associated with reward such as dopamine can impact on anxiety and other behaviour disorders of offspring." (PMID 24027581, 2013). "Others have used the well-defined leptin deficient ob/ob mouse model to determine leptin's role in stress-induced feeding and anxiety." (PMID 23898237, 2013). "Leptin deficient mice display increased depressive and anxiety–related behaviors and overexpression of leptin has been shown to exert antidepressant and anxiolytic effects." (PMID 23251447, 2012). "The pro-inflammatory responses of leptin could be associated with the anxiety-related behaviors promoted by this adipokine in the hypothalamus (lateral arcuate nucleus and paraventricular nucleus), together with other peptide hormones (ghrelin)." (PMID 40565847, 2025). "In addition, we investigated and compared the anxiety-like behaviors caused by the induction of various types of stress and the subsequent change in leptin responsiveness." (PMID 39559273, 2024). "Interestingly, a study in zebrafish with loss of function in leptin gene (lepa) has shown increased anxiety-like behaviour with reduction in aggressive behaviour." (PMID 34236575, 2021). "These associations raise interesting questions about how anxiety may be linked to leptin and smoking, however, the causative effects of these associations cannot be delineated." (PMID 34421692, 2021).
Anxiety (continued). "In adult participants, low cerebrospinal fluid (CSF) leptin in females who recently attempted suicide was associated with higher anxiety, while patients who had moderate to severe anxiety had a higher free leptin index, and leptin was positively associated with anxiety in overweight women." (PMID 34421692, 2021). "Clinicians should also take into consideration other indirect factors that are strongly associated with both leptin and anxiety, such as adiposity, when conducting and interpreting any screening measures to inform individualized treatment approaches for youth at risk of excess weight gain." (PMID 31547319, 2019). "Also, leptin-deficient mice (ob/ob) show more anxiety-like behaviors in multiple behavioral tests." (PMID 39559273, 2024). "Therefore, we cannot bluntly arrive at a conclusion that leptin plays a causal role in somatic anxiety symptoms in MDD, due to other factors that may influence the relationship between leptin and “somatic anxiety” symptoms." (PMID 35911226, 2022). "Our identified haplotype associations with substance use and anxiety measures, along with findings from previous literature suggest that genetic variations within components of the leptin system (peptide/receptor) may be linked to these psychological and behavioral outcomes." (PMID 34421692, 2021). "Thus, leptin-deficiency results in marked alterations in anxiety-related behaviors." (PMID 32789683, 2020). "Among youth with LOC eating, anxiety may be associated with higher serum leptin." (PMID 31547319, 2019). "Patients with anorexia nervosa (AN) had the lowest levels, and patients with mood disorders had higher leptin levels than patients with mental disorders other than mood disorders, anxiety or AN." (PMID 41489631, 2026). "Adiponectin, leptin, and resistin levels positively correlated with anxiety symptoms (HARS, p < 0.01)." (PMID 40565847, 2025). "Leptin also diminishes anxiety, presumably to balance the potential for starvation against the risk of predation." (PMID 40393800, 2025). "An exciting avenue for future studies would be to investigate the therapeutic utility of leptin-sensitive circuits for the treatment of anxiety and eating disorders, particularly in the context of genetic risk models." (PMID 41116115, 2025). "As shown, significant higher correlations were observed between leptin, resistin, and anxiety symptoms (HARS scores) in the symptomatic groups (p < 0.004)." (PMID 40565847, 2025). "Systemic administration of leptin has been shown to produce anxiolytic effects and removal of the leptin receptor in midbrain dopaminergic neurons results in an anxiety-like phenotype." (PMID 39559273, 2024). "The changes in serum leptin levels and its impact on hypothalamic function seem to play a significant role in reducing resistance to stress and increasing anxiety-like behaviors in animals exposed to prenatal stress." (PMID 39559273, 2024). "Further, studies have shown inhibition, knockdown and deletion of leptin signaling by targeting leptin receptors led to an increase in dopamine levels, anxiety levels and enhanced the cocaine-conditioned reward." (PMID 38660223, 2024). "Studies have shown that systemic administration of leptin produces anti-anxiety effects, and the removal of leptin receptors in midbrain dopaminergic neurons increases anxiety-like behaviors." (PMID 39559273, 2024). "Ghrelin and the adipokines leptin and adiponectin have been suggested to be involved in mood and anxiety regulation and to be altered in affective disorders." (PMID 35633817, 2022). "Anxiety PCQ behavioral scores from parents were significantly worse with antenatal expression of 11 gene variants involved with estrogen (p = 0.000005), leptin (p = 0.0002) and TNF alpha signaling (p = 0.0003)) within social communication regions." (PMID 35883654, 2022).
Anxiety (continued). "Cerebrospinal fluid leptin/body mass index significantly and negatively correlated with anxiety and serum cortisol before and after dexamethasone suppression tests." (PMID 36430254, 2022). "In leptin–saporin-injected animals, increased OFT-anxiety and SPT–anhedonia suggested that the loss of EWcp/UCN1 cells provoked mood changes but normal motor coordination and locomotor activity excluded parkinsonism." (PMID 35109869, 2022). "Secreted from adipocytes, adiponectin and leptin have been demonstrated to modulate anxiety and depressive behaviours." (PMID 35098831, 2022). "Leptin administration in animals have shown some promise for anxiety reduction, which would seem to be in contrast with our finding of a positive association with neuroticism." (PMID 33963214, 2021). "In summary, our results suggest that LEP and LEPR are linked to some measures of substance use and anxiety." (PMID 34421692, 2021). "However, limited to female patients, lower leptin serum levels were associated with a greater severity of psychopathological manifestations, including the number of panic attacks, symptoms of somatization, anxiety and phobic anxiety, and overall clinical presentation compared to the HCs." (PMID 32824625, 2020). "Instead, the possible role of leptin as a pathophysiologic mechanism in the generation of anxiety-like behavior is not completely understood." (PMID 32397542, 2020). "That is, in the case of sleep deprivation in women, the concentration of the plasma level of leptin increases more, and this increase stimulates the amygdala to control changes in anxiety and emotional stress." (PMID 31500186, 2019). "It is possible that those with both anxiety symptoms and LOC eating are at particular risk for leptin resistance and excess weight gain." (PMID 31547319, 2019). "Long-term EE for twelve months reduced adiposity, improved glucose tolerance, decreased leptin levels, enhanced motor abilities, and inhibited anxiety." (PMID 30036185, 2018). "Diabetic rats expressing low level of leptin show hyperactivity behavior with increase of total movement time, and high anxiety levels than the control group in elevated plus maze test." (PMID 30551684, 2018). "There are a number of possible mediators of the effect of diet on anxiety-like behaviour, including both peripheral and central mediators such as corticosteroids, insulin leptin, acetylcholine, serotonin, opioids and dopamine." (PMID 24027581, 2013). "Such a hypothesis is supported by findings showing that leptin plasma levels were positively correlated with BMI in reproductive women with anxiety states." (PMID 40565847, 2025). "Hitherto, our findings about the increased leptin levels in symptomatic pregnant women suggest that this adipokine exerts a key role in modulating stress-inducing high levels (somatic) of anxiety symptoms in response to anxiogenic stress responses in vulnerable pregnant women." (PMID 40565847, 2025). "Pro-inflammatory properties of leptin and resistin may contribute to the severity of anxiety symptoms." (PMID 40565847, 2025). "Leptin action on these midbrain cells does little to modulate feeding but may alter stress- and anxiety-related behaviors." (PMID 40393800, 2025). "Furthermore, we will compare anxiety-like behaviors induced by different types of stress and the resulting changes in leptin responsiveness." (PMID 39559273, 2024). "In this study, the effect of chronic social instability stress (INS) and chronic unpredictable stress (CUS) on anxiety-like behavioral responses and the level of expression of leptin and its receptor in the brain of male Wistar rats that were under maternal stress (MS) were investigated." (PMID 39559273, 2024). "Furthermore, leptin injected into the VTA reduces anxiety-like behaviors, and removal of LepR (using AAV-cre technology) from VTA enhanced anxiety-like behaviours." (PMID 40656109, 2024).
Anxiety (continued). "The polymorphism rs3828942 of LEP mentioned in the introduction is not so important for homeostatic energy regulation, as it is significant for sleep and anxiety regulation." (PMID 36294794, 2022). "Furthermore, leptin was a significant and indirect mediator of the association between clinical status (MDD or FDR-MDD) and “somatic anxiety” symptoms." (PMID 35911226, 2022). "In addition to addictive behaviors, ob/ob mice exhibit increased anxiety, and treatment with leptin results in a reduction of anxiety-like behaviors." (PMID 34421692, 2021). "In addition to the HPA axis, leptin signals to brain regions involved in the regulation of stress, anxiety, emotion, and behavior, including the hippocampus, amygdala, substantia nigra, nucleus accumbens (NAc), and the ventral tegmental area (VTA)." (PMID 34421692, 2021). "Leptin suppresses feeding, locomotion, anxiety and motivation to obtain food." (PMID 34276560, 2021). "However, previous studies report that leptin reduces anxiety by inhibition of VTA DA-LepR neurons that project to the extended central amygdala." (PMID 34276560, 2021). "In HFD induced obese animals, resistance to metabolic hormonal signals, such as leptin and insulin may explain the corresponding increases in anxiety levels." (PMID 34064242, 2021). "Leptin plays a role in food reward, feeding, locomotion and anxiety." (PMID 34276560, 2021). "The role of leptin in anxiety remains to be fully understood." (PMID 34421692, 2021). "Leptin, an adipose-derived peptide hormone, mainly regulates energy balance and also modulates several CNS functions, comprising learning, memory, and mood and anxiety regulation." (PMID 32824625, 2020). "However, many other studies have demonstrated higher leptin levels in patients with anxiety and psychological stress." (PMID 32824625, 2020). "Furthermore, Alonso-Caraballo and colleagues found that increased anxiety-like behaviours in the EPM were associated with increased weight gain and plasma leptin in male rats only." (PMID 33027912, 2020). "We hypothesized that trait anxiety would be positively related to fasting serum leptin, and that anxiety would interact with LOC eating, such that among those with LOC eating, anxiety would be more robustly associated with serum leptin." (PMID 31547319, 2019). "Taken together, examining anxiety in relation to serum leptin may help clarify those youth with LOC eating who are potentially at the highest risk for persistent LOC and adverse outcomes." (PMID 31547319, 2019). "Some studies have reported that leptin may modulate fear and anxiety behaviors through the reversal of conditioning−induced potentiation of thalamic input synapses onto the lateral amygdala." (PMID 31354416, 2019). "Only little is known about leptin's role in fear and anxiety." (PMID 31271235, 2019). "Yet, it remains unclear how anxiety relates to leptin, or if the relationship is moderated by the presence of LOC eating." (PMID 31547319, 2019). "However, more research is needed to clarify the directionality of these relationships prospectively and to better understand how anxiety relates to serum leptin in youth with LOC eating." (PMID 31547319, 2019). "Hence, it is important to address, in future studies, leptin's effects in other behavioral tests related to anxiety, social interaction, and cognitive function." (PMID 30949073, 2019). "It is plausible that acupuncture may be a novel adjunctive treatment for weight loss that can both optimise behavioural change through reducing anxiety and appetite, as well as impacting on physiological markers such as leptin, ghrelin and insulin." (PMID 30409195, 2018). "However, the possible role of leptin and resistin as a pathophysiologic mechanism in the generation of anxiety-like behavior is not completely understood." (PMID 28463967, 2017). "This may indicate that CART is a downstream component of a leptin-regulated mechanism that reduces anxiety-related behavior under stress conditions." (PMID 24624061, 2014).
Anxiety (continued). "Mutant mice that lack leptin signaling have been found to develop depressive symptoms whereas systemic and central administration of leptin in wild-type mice reduced anxiety and depressive-like behaviors." (PMID 25386150, 2014). "Repeated leptin treatment has also been shown to reduce anxiety in ob/ob mice." (PMID 24109426, 2013). "This heightened sensitivity to leptin during the winter SDs would lead to a decreased propensity to engage in food-seeking behaviors either through reductions in DA output or increases in anxiety-like behaviors." (PMID 23966906, 2013). "Indeed, two recent studies have highlighted the role of leptin and urocortin 2 signaling in the brain as sites of action that modulate thermal nociception and anxiety-like behavior, respectively." (PMID 20604941, 2010). "Similarly, after controlling our variables for BMI, leptin and resistin displayed significantly high correlations with high levels of anxiety (HARS, p < 0.005), while adiponectin showed also an association with anxiety symptoms (HARS, p = 0.01)." (PMID 40565847, 2025). "It is worth mentioning that increased circulating leptin levels were reported in individuals with acute stress displaying normal weight and BMI, supporting, thus, that leptin may enhance anxiety symptoms in vulnerable pregnant women with normal baseline weight and BMI measures, as shown herein." (PMID 40565847, 2025). "Furthermore, the developmentally low leptin levels in young females have been considered fundamental for the AN psychological and behavioral manifestations (hyperactivity, anxiety obsessiveness, and so on) that characterize this state of entrapment/entanglement." (PMID 39568611, 2024). "Leptin signaling in the amygdaloid complex itself and innervating midbrain dopaminergic neurons interacts with mesolimbic reward pathways, modulates anxiety-related behaviors (Liu, Perez, Zhang, Lodge, & Lu, 2011) and conditioned taste aversion (Han, Yan, Luo, Liu, & Wang, 2003) in rodents." (PMID 36464660, 2023). "Although individual associations were found in previous studies between blood lipid levels, blood pressure, or metabolic hormones (e.g., leptin), and levels of anxiety, it is still unknown whether changes in any of these biomarkers relate to changes in psychological status after LCDs." (PMID 35873416, 2022). "Levels of anxiety, eating behavior scores and physiological parameters (i.e., body weight, V̇O2peak, blood pressure, fasting glucose, blood lipids, and serum metabolic hormones including insulin, C-peptide, leptin, and ghrelin) were measured before and after the intervention." (PMID 35873416, 2022). "Indeed, leptin infusion into the VTA of mice decreased anxiety-like behavior." (PMID 34276560, 2021). "Therefore, uncovering the physiological impact of leptin’s developmental effects on GLP-1 inputs to the PVH may require a comprehensive evaluation of how anxiety and stress interact to regulate ingestive behavior." (PMID 33206596, 2020). "Among youth with LOC eating, anxiety may be related to greater dysregulation of serum leptin." (PMID 31547319, 2019). "It is unclear whether anxiety is associated with increased serum leptin in the absence of LOC eating, or whether LOC eating is necessary for such a relation to emerge." (PMID 31547319, 2019). "Also, leptin exhibit an antidepressant-like efficacy and ameliorates anxiety in ob/ob mice." (PMID 23579596, 2013). "In view of leptin's actions to diminish behavioral despair and anxiety via hippocampal and ventral midbrain nuclei, respectively, regions where insulin receptors are also expressed, it is interesting to speculate that these sites could be important for an influence of insulin on emotional states." (PMID 24109426, 2013).